TREM1 (triggering receptor expressed on myeloid cells 1)
Diseases named in the same sentence as TREM1 in open-access papers (continued):
Sharing a sentence is not in itself a finding about the gene and the disease.
dyslipidemia (5 papers, 2016 to 2025). "TREM-1 upregulation was demonstrated in murine and human atherosclerotic lesions in situ, and it was found to aggravate dyslipidemia-induced peripheral blood monocytosis." (PMID 33814983, 2021). "We show that factors contained in dyslipidemic serum are sufficient to modulate expression of TREM-1 and that TREM-1 in turn can synergize with dyslipidemia for augmented inflammation and foam cell formation." (PMID 27762264, 2016). "In particular, TREM-1 aggravated the dyslipidemia-induced peripheral blood monocytosis by promoting skewed monocyte differentiation from BM haematopoietic stem and progenitor cells." (PMID 27762264, 2016). "Clearly, the complex contribution of TREM-1 to monopoiesis needs to be deciphered in further investigations that can take into account the multifarious dyslipidemia-induced changes in dietary PAMPs and cytokines in vivo." (PMID 27762264, 2016). "Collectively, our findings illustrate that dyslipidemia induces TREM-1 surface expression on myeloid cells and subsequently synergizes with TREM-1 to enhance monopoiesis, pro-atherogenic cytokine production and foam cell formation." (PMID 27762264, 2016). "Considering the synergistic impact of dyslipidemia and TREM-1 on the peripheral immune compartment, we in turn assessed the potential impact of HFCD feeding on TREM-1 surface expression by peripheral blood myeloid cell subsets." (PMID 27762264, 2016). "Taken together, these results suggested that dyslipidemia distinctly increases expression of TREM-1 on all circulating myeloid cell subsets and that TREM-1-mediated signalling in turn provokes skewed monocyte differentiation in the BM, resulting in exacerbated monocytosis and atherogenesis." (PMID 27762264, 2016).
fibrosis (5 papers, 2013 to 2025). the formation of excess fibrous connective tissue in an organ or tissue in a reparative or reactive process. "In this study, we used potentially novel ligand-independent TREM-1 inhibitors in preclinical models of fibrosis and explanted SSc skin fibroblasts in order to investigate the pathogenic role of TREM-1 in SSc." (PMID 39418109, 2024). "We demonstrated the antifibrotic potential of TREM-1 blockade in systemic sclerosis (SSc) by animal model of fibrosis and SSc." (PMID 39418109, 2024). "Among these genes the most expressed canonical pathways were TREM1 signaling, hepatic fibrosis/hepatic stellate cell activation, ILK signaling, IL-17A signaling in airways cells, and production of nitric oxide and reactive oxygen species in macrophages." (PMID 26649052, 2016). "Furthermore, pDAP12, the marker for TREM-1 activation was elevated in skin biopsies from patients with early-stage SSc, as well as in the bleomycin-induced fibrosis model." (PMID 39418109, 2024).
Insulin resistance (5 papers, 2019 to 2024). Increased resistance towards insulin, that is, diminished effectiveness of insulin in reducing blood glucose levels. "Interestingly, TREM-1 expression was higher in diabetic obese as compared to non-diabetic obese patients, suggesting an association between insulin resistance and TREM-1 activation." (PMID 36699032, 2022). "Triggering receptors expressed on myeloid cells 1 (TREM1) plays a significant role in the induction of inflammatory response in innate immunity, synergistically with other molecules such as Toll-like receptors (TLRs), and is involved in the pathogenesis of insulin resistance in obese individuals." (PMID 39264906, 2024). "In parallel, hyperinsulinemia was more pronounced in WT than in TREM-1 KO HFD mice, witnessing the presence of insulin resistance." (PMID 36699032, 2022). "Here we show that TREM-1 is expressed and functional in (pre-) adipocytes and that its genetic ablation confers favorable effects in HFD mice including reduction of weight gain, inflammation, and insulin resistance." (PMID 36699032, 2022). "Finally, we could not determine whether the reduction in insulin resistance was due to weight differences or to a more direct protective effect of the Trem1 deletion." (PMID 36699032, 2022).
keratitis (5 papers, 2014 to 2025). A corneal disease that is characterized by inflammation of the cornea. "A study on the P. aeruginosa murine keratitis model showed that TREM1 has an inflammatory amplification effect during infection." (PMID 38694515, 2024). "They first confirmed that TREM-1 expression was elevated in the corneas of patients with fungal keratitis compared to normal corneas, and similarly, in a murine model of Aspergillus fumigatus keratitis." (PMID 41226426, 2025). "It has been reported that after infection with P. aeruginosa, TREM-1 mRNA expressions were significantly increased in both human and mouse corneas, which contribute to amplifying corneal inflammation in P. aeruginosa keratitis by regulating TLR signaling and immune responses." (PMID 31649630, 2019). "In addition, it has been reported that TREM-1 can modulate immune responses to P. aeruginosa keratitis." (PMID 26963514, 2016). "Furthermore, they examined TREM-1 suppression by tacrolimus in both in vitro RAW264.7 macrophage cells and an in vivo murine model of Aspergillus fumigatus keratitis." (PMID 41226426, 2025).
papillary thyroid cancer (5 papers, 2021 to 2025). "Based on data coming from The Cancer Genome Atlas (TCGA), TREM-1 expression was compared between papillary thyroid carcinoma (n = 512) and normal thyroid tissues (n = 58)." (PMID 35875168, 2022). "High expression of TREM1 in papillary thyroid cancer (PTC) could promote an immunosuppressive microenvironment by enhancing Treg infiltration and decreased CD8+T cells infiltration." (PMID 39744496, 2025). "However, the biological function of TREM-1 in papillary thyroid carcinoma (PTC) remains unknown." (PMID 34122331, 2021). "The immunohistochemical results (achieved using Human Protein Atlas immunohistochemical images) demonstrated that TREM-1 protein expression was significantly upregulated in papillary thyroid carcinoma tissue compared with non-malignant tissues." (PMID 35875168, 2022). "TREM-1 mRNA expression was significantly higher in human papillary thyroid carcinoma tissues in comparison to non-tumoral thyroid tissues (p<0.0001)." (PMID 35875168, 2022).
periodontal disease (5 papers, 2013 to 2025). "Upon microbial stimulation, TREM-1 expression is significantly upregulated, contributing to periodontal disease progression." (PMID 41226426, 2025). "Several studies have investigated TREM-1 and PGLYRP1 in the context of periodontal disease and recently TREM-1 has been suggested as a candidate marker for new treatment strategies against periodontal diseases." (PMID 33536478, 2021).
thyroid cancer (5 papers, 2020 to 2024). "Cytoplasmic HMGB3 activates nucleic acid-mediated TLR3/NF-κB signaling, and extracellular HMGB3 interacts with the transmembrane receptor triggering receptor expressed on myeloid cells (TREM1 and CD354) in thyroid cancer." (PMID 39062899, 2024). "TREM-1 may promote thyroid cancer progression through immune-related pathways." (PMID 34122331, 2021). "Among the four methylation-driven genes, the high expression level of TREM1, BIRC7, and SLC26A7 prognosticated low survival rate, whereas RDH5 acted as protective genes to suggest good prognosis of thyroid cancer." (PMID 32296463, 2020).
acute pancreatitis (4 papers, 2012 to 2019). An acute inflammatory process that leads to necrosis of the pancreatic parenchyma. "Similar, pretreatment with TREM1 inhibitor improved the hepatic and renal dysfunction in experimental model of severe acute pancreatitis." (PMID 24358193, 2013). "Patients with acute pancreatitis (AP) are characterized by a high expression level of TREM-1 mRNA in leukocytes." (PMID 22611379, 2012). "The modulation of TREM-1 signaling by the use of a synthetic peptide such as LP17 appears to be a promising therapeutic approach for the treatment of acute pancreatitis complicated by injury of the intestinal mucosa barrier." (PMID 22611379, 2012). "In acute pancreatitis, expression of TREM-1 correlated with disease severity." (PMID 29454501, 2019).
chronic kidney disease (4 papers, 2013 to 2023). Impairment of the renal function secondary to chronic kidney damage persisting for three or more months. "Moreover, TREM-1 was also induced and accelerated inflammatory renal injury in IgA nephropathy and an elevation of sTREM-1 was reported in patients with chronic kidney disease on haemodialysis." (PMID 37886760, 2023).
Hepatitis (4 papers, 2016 to 2022). Inflammation of the liver. "Thus, TREM1 deficiency seemed to attenuate LCMV-induced hepatitis." (PMID 27328755, 2016). "More recently, Trem1−/− mice were reported to be protected from LCMV-induced hepatitis despite normal CD8 T cell responses." (PMID 28900132, 2017).
non-alcoholic fatty liver disease (4 papers, 2020 to 2025). "In non‐alcoholic fatty liver disease, inhibition of TREM‐1 reduces the inflammation and lipid accumulation." (PMID 34750987, 2021). "Furthermore, pharmacological inhibition of TREM-1 has been shown to reduce inflammation and lipid accumulation in diet-induced nonalcoholic fatty liver disease (NAFLD) models." (PMID 41226426, 2025). "Expression of TREM1 is upregulated, and overexpression of TREM1 increases lipid accumulation-related genes via the PI3K/AKT signaling pathway in non-alcoholic fatty liver disease (NAFLD)." (PMID 33297569, 2020).
pancreatic adenocarcinoma (4 papers, 2021 to 2025). "This analysis identified the second highest correlation between TREM1 gene expression and the classically activated macrophage signature in pancreatic adenocarcinoma (PAAD)." (PMID 40917508, 2025).
peritonitis (4 papers, 2014 to 2025). Inflammation of the peritoneum (tissue that lines the abdominal wall and covers most of the organs in the abdomen). "TREM-1 expression is significantly upregulated on neutrophils and macrophages during Pseudomonas aeruginosa-induced peritonitis, which may be associated with increased mortality." (PMID 41226426, 2025). "Inhibition of TREM-1 signaling using the TREM-1-Fc fusion protein has been shown to prolong survival in animal models of P. aeruginosa-induced peritonitis by blocking TREM-1-mediated immune activation." (PMID 41226426, 2025). "We here reported that a TREM-1 inhibitory peptide targeting the endothelium was able to reduce endothelial cell activation and to confer protection during experimental peritonitis in mice." (PMID 31632399, 2019). "It decreased LPS induced TREM-1 up-regulation and cell activation, neutrophils extravasation, and improved median survival time during experimental peritonitis in mice." (PMID 31632399, 2019). "Putative ligands for TREM-1 have been described on the surface of human platelets and on murine granulocytes during experimental peritonitis and endotoxaemia." (PMID 24453980, 2014).
pulmonary fibrosis (4 papers, 2016 to 2025). Chronic progressive interstitial lung disorder characterized by the replacement of the lung tissue by connective tissue, leading to progressive dyspnea, respiratory failure, or right heart failure. "In conclusion, we found the expression of TREM-1 was increased in lung tissues from mice with pulmonary fibrosis." (PMID 26738569, 2016). "In conclusion, we found that 1) the expression of TREM-1 was increased significantly in a mouse model of BLM-induced pulmonary fibrosis; 2) TGF-β1 increased expression of the TREM-1 by interfering AP-1 transcriptional pathway in mouse macrophages." (PMID 26738569, 2016). "TGF-β1 is a central node in the pulmonary fibrosis pathogenesis pathway, while TREM-1 activation dramatically increases the expression of TGF-β family genes." (PMID 26738569, 2016). "We found that TGF-β1 expression was positively correlated to the expression of TREM-1 significantly, and expression of the TREM-1 was upregulated in the lungs of mice with BLM-induced pulmonary fibrosis." (PMID 26738569, 2016). "Pathway analysis revealed that airway immunity, inflammatory host responses, and epithelial repair and remodeling were modulated by VD, as pathways including wound healing signaling pathway, pulmonary fibrosis idiopathic signaling pathway and TREM1 signaling were clustered." (PMID 37407993, 2023). "TGF-β1 may form a positive feedback with TREM-1 and accelerate the progression of pulmonary fibrosis." (PMID 26738569, 2016). "Therefore, the expression of TGF-β1 and TREM-1 is mutually synergistic and a positive feedback can be formed that speeds up the development and progression of pulmonary fibrosis." (PMID 26738569, 2016). "These previous findings prompted us to speculate that there is a putative link between TREM-1 and pulmonary fibrosis." (PMID 26738569, 2016). "In this study, we determined whether TGF-β1 regulated the expression of TREM-1 in a mouse model of pulmonary fibrosis." (PMID 26738569, 2016). "However, there has been little study on TREM-1 in the pathogenesis of pulmonary fibrosis." (PMID 26738569, 2016). "Interestingly, both GF9 and GA31-LPC were effective in preventing and treating BLM-induced pulmonary fibrosis, suggesting that anti-inflammatory mechanisms of pan-TREM-1 and macrophage-restricted TREM-1 blockade may importantly contribute to the therapeutic effects in chronic inflammatory diseases." (PMID 41404075, 2025). "Triggering receptor expressed on myeloid cells 1 (TREM-1) increases the expression of TGF-β family genes, which are known as profibrogenic cytokines in the pathogenesis of pulmonary fibrosis." (PMID 26738569, 2016). "It is not clear whether modification of the expression of TREM-1 and TGF-β1 affects pulmonary function or progression of the pulmonary fibrosis." (PMID 26738569, 2016).
renal cell carcinoma (4 papers, 2021 to 2025). "We confirmed the significance of our findings by demonstrating TREM-1 expression on tumor-infiltrating monocytes and neutrophils in renal cell carcinoma (RCC) donors." (PMID 35223446, 2021). "TREM1 could also predict the prognosis of renal cell carcinoma." (PMID 34221733, 2021). "Soluble TREM-1 levels were also investigated in human renal cell carcinoma (RCC)." (PMID 35875168, 2022). "Similarly, we detected TREM-1 and Trem2 expression in myeloid cells in the RENCA model of renal cell carcinoma (RCC)." (PMID 35223446, 2021).
renal fibrosis (4 papers, 2013 to 2025). A final common manifestation of a wide variety of chronic kidney diseases characterized by glomerulosclerosis and tubulointerstitial fibrosis. "If urinary TREM-1/TREM-2 ratio can better serve as a biomarker of renal fibrosis in specific pathological types need to be further studied." (PMID 34176389, 2021). "Urinary TREM-1/TREM-2 ratio was a potential biomarker for the diagnosis of renal fibrosis in CKD patients." (PMID 34176389, 2021). "Subsequently, we investigated the contribution of TREM1-DAP12 in renal fibrosis by subjecting wild-type, TREM1/3 KO and DAP12 KO mice to UUO model." (PMID 24358193, 2013). "In summary, our study demonstrated that the urinary TREM-1/TREM-2 ratio could well predict renal fibrosis severity in CKD, which suggested this will serve as a novel independent non-invasive biomarker to monitor the progression of kidney fibrosis in CKD." (PMID 34176389, 2021). "Renal fibrosis was comparable in WT, TREM1/3 double KO and DAP12 KO mice." (PMID 24358193, 2013). "Accordingly, this study was designed to determine the expression of urinary TREM-1 and TREM-2 via qPCR indicate CKD and renal fibrosis." (PMID 34176389, 2021). "Urinary TREM-1 and TREM-2 mRNA detection and the TREM-1/TREM-2 ratio served as a non-invasive biomarker of renal fibrosis." (PMID 34176389, 2021). "In recent years, researchers found that TREM-1 participated in the progression of CKD and renal fibrosis." (PMID 34176389, 2021). "If the urinary mRNA expression of TREM-1 and TREM-2 have correlated with CKD and renal fibrosis was still unknown." (PMID 34176389, 2021). "Our study firstly indicated that the mRNA ratio of urinary TREM-1/TREM-2 was related to CKD and may serve as a potential non-invasive biomarker of renal fibrosis." (PMID 34176389, 2021). "In our data, we found that in none-mild renal fibrosis human kidney tissue, the expression of TREM-1 was higher than TREM-2." (PMID 34176389, 2021). "TREM-1 does not play a crucial role in the acute phase after AKI, whereas in a model of renal fibrosis, might be detrimental due to a direct effect on renal inflammation and M1 macrophages activation." (PMID 31354698, 2019).
thoracic aortic aneurysm (4 papers, 2022 to 2025). An aneurysm formed in the wall of the proximal portion of the descending aorta proceeding from the arch of the aorta. "Another study reported an Il1rn+/Trem1+ macrophage subpopulation in thoracic aortic aneurysm and dissection, and Il1rn and Trem1 were also relatively highly expressed in the Mac_TREM2 subtype we found." (PMID 40463378, 2025). "Recently, an Il1rn+/Trem1+ macrophage subpopulation was identified as a cellular target for mitigating the progression of thoracic aortic aneurysm and dissection by using scRNA‐seq." (PMID 39720896, 2024).
ventilator-associated pneumonia (4 papers, 2010 to 2017). Serious INFLAMMATION of the LUNG in patients who required the use of PULMONARY VENTILATOR. "The gene TREM1 (Triggering Receptor Expressed on Myeloid cells 1) helps stimulate immune response factors and has been proposed as a biomarker for P. aeruginosa ventilator associated pneumonia (VAP)." (PMID 24086587, 2013). "Carriers of the TREM-1 25 T allele appear to have a greater likelihood of developing ventilator-associated pneumonia." (PMID 24049659, 2013). "A soluble form of TREM-1, namely sTREM-1, is increased in the bronchoalveolar lavage (BAL) of patients with ventilator associated pneumonia (VAP), and in the serum of patients with sepsis, with bacterial meningitis and with acute pancreatitis." (PMID 20920231, 2010).